RN7SL664P (RNA, 7SL, cytoplasmic 664, pseudogene)
Gene: Miscellaneous RNA gene on chromosome 3 (48,094,801 to 48,095,105, reverse strand). Ensembl gene ENSG00000265078.
Homologues: Orthologues: chimpanzee Metazoa_SRP (99% identical), macaque Metazoa_SRP (93% identical). Paralogues in human: RN7SL1 (86% identical), RN7SL2 (85% identical), RN7SL3 (85% identical), RN7SL709P (82% identical), RN7SL230P (82% identical), RN7SL679P (82% identical), RN7SL296P (81% identical), RN7SL786P (81% identical), RN7SL126P (81% identical), RN7SL408P (81% identical), RN7SL448P (81% identical), RN7SL451P (81% identical), and 703 more.